BRAF (B-Raf proto-oncogene, serine/threonine kinase)
Diseases named in the same sentence as BRAF in open-access papers (continued):
Sharing a sentence is not in itself a finding about the gene and the disease.
cancer (continued). "Consequently, YAP and TEAD activity may function as a critical regulator, modulating the extent of adaptive changes in RTK signalling following MAPK-pathway inhibition in BRAF V600E-mutant cancers." (PMID 40332222, 2025). "In addition to the inherently aggressive biology of BRAF-mutated CRC, poor response to anti-cancer therapy could contribute to poor OS." (PMID 38982444, 2024). "Furthermore, we performed CIC activities analysis and found that most of the steps, including priming and activation (Step 3) as well as trafficking of immune cells to tumors (Step 4) were activated in PTC with RET-MT or BRAF-MT, whereas recognition of cancer cells (Step 6) was suppressed." (PMID 38734621, 2024). "However, because the V600E mutation accounts for about 90% of BRAF mutation seen in human cancer 18, mutation selection is not the primary means to achieve the “just-right” levels of oncogenic ERK signaling." (PMID 36778401, 2024). "We could observe some pathogenic variants in different cancer-associated genes including BRAF, FGFR2 or ERBB3 that, although not currently available in the clinical practice, may be considered for treatment in future clinical trials." (PMID 39003322, 2024). "However, because the V600E mutation accounts for about 90% of BRAF mutation seen in human cancer, mutation selection is not the primary means to achieve the ‘just-right’ levels of oncogenic ERK signaling." (PMID 38921956, 2024). "The detection of the BRAF V595E gene mutation in urine samples could provide a non-invasive method for diagnosing these cancers." (PMID 39272320, 2024). "The Central America and Caribbean consensus on the management of mCRC recommended a first-line doublet (FOLFOX or FOLFIRI) or triplet (FOLFOXIRI) with an anti-VEGF antibody for patients with BRAF-mutated non-resectable cancer and for whom debulking surgery can be objective." (PMID 40171464, 2024). "The female sex is also more associated with hypermethylation, microsatellite instability, BRAF V600E mutation and CpG island methylator phenotype (CIMP)-high, which is consisted with the genetic architecture of RCRC and leads to more aggressive forms of cancer." (PMID 38398251, 2024). "A better understanding of BRAF mutations, especially class II and III mutations, may enable the rational design of new targeted therapies and the development of next-generation drug combination strategies to treat BRAF-mutant cancers, including NSCLC25,33." (PMID 38627602, 2024). "Given this, it appears that in the case of BRAF-mutant cancers, treatments are influenced by the presence and type of BRAF mutation rather than directly by age, though precise regimens may differ by population type." (PMID 38539548, 2024). "Previous studies have found that the BRAF V600E mutation in PTC is associated with glucose transporter 1 (GLUT1) overexpression, which may contribute to the initiation of a glycolytic phenotype in cancer cells." (PMID 38902782, 2024). "The rarity of non-colorectal epithelial BRAF-mutated cancers compromises their clinical studies." (PMID 38612902, 2024). "In contrast to the other cancer types discussed, in CRCs, non-p.V600E mutations occur at higher frequencies than BRAF p.V600E in younger patients and men, are located on the distal colon, display low-grade histology, and have a longer median OS in response to chemotherapy." (PMID 38539548, 2024). "However, mutations caused by NRAS, KRAS, BRAF, PI3KCA, and Akt activation in cancers may confer the cancer cells’ therapeutic resistance to cetuximab and render it a less effective anti-cancer agent." (PMID 37507626, 2024). "Furthermore, despite thorough sequencing studies, no significant point mutations, whether germline or somatic, were identified in frequently mutated cancer-associated genes such as KRAS, BRAF, and PIK3CA, concerning SFT." (PMID 39364485, 2024). "Hence, there were 100 carcinomas (29.4%) with neither RAS nor BRAF V600E or TERT promoter variants (eTable 1 in Supplement 1)." (PMID 38758552, 2024).
cancer (continued). "Additionally, as an increasing number of targeted therapies are being developed, cfDNA analysis may be able to identify cancers eligible for personalized approaches (such as HER2 or BRAF targeted therapy or platinum-based chemotherapy for BRCA2 mutated PC)." (PMID 37685923, 2023). "In human cancers with frequent (V600E) BRAF mutation, it is widely recognised that intratumoral heterogeneity exists; however, intratumoral BRAF mutation heterogeneity has not yet been described in canine cancer." (PMID 37570213, 2023). "Moreover, we devised a therapeutic strategy involving a type I BRAF inhibitor to strengthen the effects of sotorasib addiction; this strategy may provide clinical benefit for patients with cancer." (PMID 37386628, 2023). "Therefore, the hyperactivation of the BRAF/MEK/ERK pathway in many cancer types may suppress BIM protein level and evade apoptosis, whereas therapies targeting this pathway have been recognized as leading to the accumulation of BIM and induction of apoptosis." (PMID 37835493, 2023). "Additionally, it also has been reported that YAP may be associated with resistance to cancer target therapy in cancer cells harboring NRAS, KRAS, or BRAF mutations 22-25." (PMID 36619222, 2023). "Therefore, the development of dual EGFR/BRAF inhibitors is a promising approach in cancer therapy." (PMID 37240450, 2023). "Therefore, developing dual EGFR/BRAF inhibitors is a promising approach in cancer therapy." (PMID 38138441, 2023). "Also, there is as yet no way to clinically predict the therapeutic efficacies of BRAF-mutated cancers to BRAF and MEK inhibitors." (PMID 36624452, 2023). "The study reveals a diverse set of biochemical and proliferative responses to BRAF V600E degradation: some cancer cells are killed by BRAF degradation, while others utilize additional oncogenic drivers, such as Src kinase phosphatidylinositol 3-kinase, to resist the effect of BRAF degradation." (PMID 38136350, 2023). "The effect of BRAF inhibitors in non-BRAF mutated cancers has reportedly been controversial." (PMID 37733241, 2023). "Considering that other cancer types harboring the BRAF V600E mutation may not respond to BRAF-targeted therapy, how such cancer cells would respond to SJF-0628-directed BRAF degradation remains unanswered." (PMID 38136350, 2023). "In our opinion, there might also be a situation in which the ipsilateral or contralateral PTC additional foci without the BRAF V600E mutation metastasize to the lymph nodes, so they are not presented in the cancer genetic profile." (PMID 37894308, 2023). "Intuitively, this is because, although cancer cells may use different intracellular signaling pathways to evade the effects of BRAF inhibitors, these alternative pathways are inherently less energetically efficient, leading to a lower overall fitness and growth rate of the population." (PMID 36853375, 2023). "Similarly, several studies have demonstrated that cancer cells develop resistance to BRAF inhibitors by overexpressing growth factor receptors at their surface, including KIT, c-MET, EGFR and PDGF-receptor-β (PDFGR-β), leading to MAPK pathway reactivation despite BRAF inhibition." (PMID 37435488, 2023). "The lack of association in patients with BRAF mutant cancers was unlikely to be due to the small numbers of samples (n = 120) since we observed this effect in a much smaller group with NRAS mutant cancers (n = 44)." (PMID 36790221, 2023). "Additionally, trametinib is also recommended by BRAF and MAP2K1 alterations, as well as new molecular evidence, such as G6PD (mutation and high overexpression), CDKN2A (deletion and underexpression) and due to the genetic dependency of MAP2K1 in BRAF-mutant cancer cell lines." (PMID 37207338, 2023). "Therefore, the adoption of TSR, BRAF and MSI as prognostic variables into current daily diagnostics might improve the risk evaluation for cancer recurrence or metastasis." (PMID 37344790, 2023).
cancer (continued). "As a result, from recent progress in cancer research, there is an emerging number of endogenous substances associated with inflammation and cancer to choose between, e.g., NF-κB, IL-6, IFN-γ, TNF-α, enzyme indoleamine-2,3-dioxygenase (IDO), and BRAF gene mutations." (PMID 37631245, 2023). "Physician should also be aware that the poor prognosis of synchronous cancers might be independent of genetic factors such as BRAF mutations, MSI-high, and CIMP-high due to unidentified molecular events caused by the genetic or environmental background." (PMID 37667167, 2023). "For some unknown reason, 25% of them did not have the silenced MLH1 gene and eventually developed BRAF-mutated MSS cancer." (PMID 37620872, 2023). "A BRAF mutation was detected in the first blood draw, a subsequent sample indicated remission, and then a new pathogenic mutation in KRAS was detected in a third blood draw, suggesting cancer recurrence, which could prompt clinical staff for further follow-up." (PMID 37218906, 2023). "Indeed, studies have shown that BRAF mutation status influences the treatment response in human cancers, and there is evidence for a different therapeutic response when comparing BRAF mutated vs. non-mutated canine cancers." (PMID 37570213, 2023). "Thus, SSA with BRAF mutations and TA/TVA with KRAS mutations may have a selective advantage for progressing to carcinoma when their TSGs are hypermethylated and inactivated through Fn infection." (PMID 37772997, 2023). "Given that BRAF is frequently hyperactivated in various human cancers, we explored whether BRAF is an authentic substrate of the CRL3-SPOP complex, and whether BRAF activity is dysregulated in SPOP-mutated cancers." (PMID 36585710, 2022). "The reasons for this divergence involving KRAS and BRAF mutations in cancer cells lacking Furin are not presently clear, but several mechanisms may be postulated." (PMID 35267511, 2022). "Along with the scientific and deeper understanding for pathophysiology mechanism of HCC, recent researches have revealed the role of BRAF in HCC, which long non-coding RNA of BRAF may be another mechanism of cancer proliferation and tyrosine kinase inhibitors escape in HCC." (PMID 35912221, 2022). "First, the stratification by KRAS and BRAF mutations may not be present in this specific subpopulation, as the patients involved in this study received surgery of the primary cancer without removing the metastasis." (PMID 35587572, 2022). "It has been reported that inhibition of the MAPK pathway activates the JAK2/STAT3 pathway, and autocrine Interleukin 6 (IL-6) secretion and subsequent JAK2/ STAT3 activation may represent an unexpected route to overcome targeted inhibition of the MAPK pathway in BRAF mutant cancers." (PMID 36430869, 2022). "Together, these data show BRAF V600 status plays an important role in determining the immunomodulatory lipid profile and lipid trafficking, which may inform future combination therapies to improve patient response to BRAF inhibitor therapy across cancers." (PMID 35565240, 2022). "Furthermore, persister cancer cells able to tolerate BRAF and MEK inhibitors performed a reversible translation reprogramming which benefited survival, resulting from an increased N6‐methyladenosine (m6A) modification in the untranslated regions of a subset of mRNAs." (PMID 35023619, 2022). "However, more investigation is needed to better understand how BRAF and lipid signaling may contribute to oncogenic and transformative potential in healthy cells and cancer cells." (PMID 35565240, 2022). "Although mutations in BRAF may affect malignancies in several cancers, functional analysis of BRAF V600E and other mutations has not been reported in HCC." (PMID 35163468, 2022). "Furthermore, according to these authors, a subpopulation of BRAF-mutant cancer cells may develop that is resistant to the primary inhibitor elevated levels of CRAF protein." (PMID 36499382, 2022).
cancer (continued). "However, during the initial treatment stages, MAPK and BRAF inhibitors could boost the immune response against cancers, unless the patient develops resistance." (PMID 35628540, 2022). "Interestingly, Nichols and colleagues demonstrated that in several MAPK pathway mutant cancer-driven cancers, including non-V600E, class 3 BRAF mutant-driven cancers, NF1 deletion-driven cancers, and KRAS G12C mutant cancers, SHP2 inhibition is effective at inhibiting downstream MEK/ERK signaling." (PMID 35905710, 2022). "Moreover, cancer-associated BRAF mutations disrupted the BRAF-SPOP interaction and allowed BRAF to evade SPOP-mediated ubiquitination, thereby upregulating MAPK/ERK signaling and enhancing the neoplastic phenotypes of cancer cells." (PMID 36585710, 2022). "Additionally, the minimum diameter of the nodules investigated in the case group was 0.5 cm, primarily because examining smaller nodules would allow even smaller cancer nests to be used for BRAF V600E testing via fine needle aspiration, resulting in a higher false-negative rate." (PMID 35356255, 2022). "The author also attempted to correlate BRAF mutations class with mutant allele fraction, however the results from these analyses might be biased and were not consistent across cancer types." (PMID 36275468, 2022). "Therefore, the combination of ERK inhibitors and BRAF or MEK inhibitors could be used in cancer therapeutics." (PMID 36233210, 2022). "Genetic alterations in BRAF may occur in the forms of point mutation or fusion mutation, leading to excessive activation of the MAPK pathway, uncontrolled cell proliferation, apoptotic escape, and finally cancer formation." (PMID 36430869, 2022). "BRAFV600E, which accounts for 90% of BRAF mutations in human cancers and has high catalytic activity alone, does not require dimerization for function, which is one of the important reasons for the high degree of malignancy of BRAF-mutant PTC." (PMID 35136031, 2022). "Nevertheless, how the BRAF V600E-MAPK/ERK axis regulates SERPIND1 at the molecular level is still unknown and requires identification of key transcription factors which may act as critical regulators of BRAF V600E-MAPK/ERK-dependent gene regulation in several types of cancer." (PMID 35163468, 2022). "However, innate or acquired resistance to BRAF inhibitors can occur in some BRAFV600E-positive cancers, and the presence of the mutation does not always correlate with clinical response to BRAF inhibitors." (PMID 35324835, 2022). "Previous studies have shown that lung carcinogenesis is attributed to the gain-functional mutation of several cancer-associated genes, including the epidermal growth factor receptor (EGFR), Kirsten rat sarcoma viral oncogene homolog (KRAS), and v-raf murine sarcoma viral oncogene homolog B1 (BRAF)." (PMID 34422661, 2021). "It was found that BRAF V600E, RET/PTC1 and TERT mutations were associated with aggressive characteristics, whereas BRAF K601E, HRAS, NRAS, KRAS, PAX8-PPARy mutations and tumors with no mutations are significantly less likely to be associated with high risk cancers." (PMID 33910629, 2021). "Notably, these studies suggest that the combined benefits of BRAF inhibition with T cell-directed immunotherapies may extend beyond BRAF-mutant or BRAFi-sensitive cancers." (PMID 34025662, 2021). "The set of genes proximate to these IS was significantly enriched in two datasets of cancer genes, including cancer drivers (genes such as BRAF, PIK3R1, RELN and TIAM2) suggesting that some koalas may harbour ERVs that could confer increased cancer susceptibility." (PMID 33637755, 2021). "In a similar manner to BRAF, mutationally activated RAS is reported to induce autophagy in a number of cancers, although the presence of a RAS mutation may not be predictive of sensitivity to chloroquine or other autophagy/lysosomotropic agents as it may be context-dependent." (PMID 34298710, 2021).
cancer (continued). "We used publically available data from the cancer cell line encyclopaedia (CCLE) database to search for mutations in EGFR, ERBB2, ERBB3, ERBB4, KRAS and BRAF that might predispose to a different response to anti-HER2 therapies or PI3K or MAPK pathway inhibition." (PMID 33933113, 2021). "Cancer is spatially and temporally heterogeneous, and recurrent tumors may not have the BRAF V600E mutation." (PMID 34168268, 2021). "It cannot be ruled out that BRAF mutations found in early stage cancer might be replaced by new, more powerful drivers as the cancer progresses." (PMID 34884530, 2021). "Nevertheless, our findings also imply its antimetastatic character in BRAF-mutated cells, indicating that the expressional status and functions of FRMD5 may not be dependent on the type of cancer tissue but rather on genetic alternations in cancer cells." (PMID 34201607, 2021). "Therefore, early diagnosis is a crucial factor in treating this type of cancer for which two therapies have been devised so far: one based on BRAF small molecule inhibitors, and the other one on monoclonal antibodies specific for cytotoxic T lymphocyte–associated antigen 4 (CTLA-4)." (PMID 33802088, 2021). "However, the full spectrum of BRAF fusions in human cancer remains incomplete." (PMID 33716974, 2021). "Therefore, there is a need for new and innovative therapies to address BRAF-driven cancers." (PMID 33568647, 2021). "Moreover, mutations of RAS, BRAF, MEK1, and MEK2 could cooperate with CDKN2A loss in different cancers." (PMID 33807122, 2021). "We could not identify any obvious alterations of cancer relevance in the transduced cell lines, including BRAF mutations, when compared to their respective controls." (PMID 32605315, 2020). "Hyperactive MAPK signaling exists in over 85% of cancers, which is caused directly by genetic alterations of its upstream activators or components, including RTKs, Ras, and BRAF, or indirectly by those independent of Ras or RAF, and significantly promotes disease progression." (PMID 32807225, 2020). "In addition, BRAF amplification (BRAFAMP) can also cause hyperactivation of MAPK signaling, which plays essential roles in the acquired resistance to MAPK inhibitor therapy in cancers harboring BRAFV600E." (PMID 33489866, 2020). "Interestingly, we found that mutations in this region of EGFR, BRAF, ERBB2, and MAP2K1 were mutually exclusive, which is consistent with a previous report that suggested one driver mutation is sufficient cancer initiation or development." (PMID 32757330, 2020). "Importantly, this resistance to SHP2 inhibition may also occur in KRAS or BRAF mutant cancers wherein FGFRs are feedback activated due to MAPK inhibition, as evidenced by the observations in SW1736 cells." (PMID 32076487, 2020). "Thus, increasing HDAC3 expression may overcome resistance to anti-cancer drugs, including BRAF and MEK inhibitors." (PMID 32626712, 2020). "Second, the survival of patients with BRAFAMP and IDH1/2MT was comparable to that of patients with BRAF mutations and greater than that of patients with BRAFAMP and IDH1/2WT, probably because the IDH1/2 mutation and 2-HG can induce oxidative stress, autophagy, and apoptosis in cancer cells." (PMID 33489866, 2020). "Furthermore, there was a strong and borderline significant trend to a worse still prognosis for BRAF mutant MSS cancers with APC mutations, compared to those without." (PMID 32384699, 2020). "Therefore, from a clinical standpoint, several cancers with terribly poor prognosis could benefit from novel insights derived from these data and combining immune-depletion with BRAF inhibitors." (PMID 32664587, 2020).